PTH (parathyroid hormone)
Diseases named in the same sentence as PTH in open-access papers (continued):
Sharing a sentence is not in itself a finding about the gene and the disease.
osteoporosis (continued). "Herein, we explored parathyroid hormone (PTH) and PTHR gene variant susceptibility to osteoporosis and their association with various circulating BTM and inflammatory markers in postmenopausal women of Arab ethnicity." (PMID 34977236, 2021). "Parathyroid hormone (PTH) is classically considered as a bone catabolic agent, but can elicit anabolic effects if administered correctly for treating osteoporosis." (PMID 34064134, 2021). "Another potential mechanism for explaining the link between atherosclerosis and osteoporosis is bone anabolic pathways such as canonical Wnt and parathyroid hormone (PTH) signaling." (PMID 34641970, 2021). "Low BMD (osteoporosis and osteopenia) reported in 6 studies, persistent HC due to persistent hyper-PTH reported in 3 studies, AVN or ONF in 2 studies, and osteomalacia in one study." (PMID 34071098, 2021). "In one such study, it was shown that vitamin K and PTH have a synergistic effect on osteoblast differentiation and hence bone formation in rats with osteoporosis." (PMID 33925324, 2021). "Elderly patients suffer from osteoporosis due to variations in biological molecules such as estrogen, growth hormones, or parathyroid hormone, leading to poor osteogenesis." (PMID 34134765, 2021). "Currently, PTH is the only FDA-approved drug for osteoporosis in the U.S., which has a clinical use of 2 years." (PMID 33925324, 2021). "Previous animal experiment revealed definitely curative effects that PTH treatment and recombinant teriparatide treatment are beneficial in the management and prevention of OA, osteoporosis, and bone fracturing." (PMID 34381493, 2021). "Our study showed that medication (mainly focusing on bisphosphonates and parathyroid hormone analogs) was the most frequently identified intervention among osteoporosis-related RCTs." (PMID 34531824, 2021). "Although several drugs, such as bisphosphonates and parathyroid hormone, are currently used to treat osteoporosis, they are ineffective against osteoporosis that has already developed." (PMID 33811248, 2021). "The current treatments of osteoporosis, e.g., estrogen, bisphosphonates, and Parathyroid hormone (PTH), have limitations, including side effects, high cost, and poor patient compliance." (PMID 33805517, 2021). "PTH on daily administration has shown promise in augmenting bone formation and has been successful in treating osteoporosis." (PMID 33925324, 2021). "The anabolic effect is exerted by low and intermittent concentrations of PTH, and has been applicable to osteoporosis treatment by daily injections of PTH." (PMID 34068220, 2021). "Teriparatide, a recombinant form of the bioactive portion of parathyroid hormone (1–34 amino acids), is used to treat osteoporosis, prevent osteoporotic fractures, and enhance fracture healing due to its net anabolic effect on bone." (PMID 34461961, 2021). "Parathyroid hormone (PTH), approved for osteoporosis therapy, is expected to improve fracture healing." (PMID 34502206, 2021). "Parathyroid hormone (PTH) and sclerostin inhibitor (SOSTi) are bone anabolic agents that are administered to patients with osteoporosis." (PMID 34140410, 2021). "Conversely, vitamin D has a stimulating effect on both calcium and phosphate homeostasis, playing a key role in providing adequate mineral for normal bone formation.High levels of PTH and/or low levels of Vitamin D can promote the onset of osteoporosis." (PMID 34876084, 2021). "Elevated serum 25(OH)D levels increase BMD by increasing the absorption of calcium and phosphorus from the intestine by reducing PTH, preventing osteoporosis." (PMID 33922027, 2021). "PTH increases calcium levels by stimulating osteoclasts, resulting in resorption of bones, which exacerbates osteoporosis in older adults." (PMID 33552763, 2021). "The attenuation of canonical Wnt signaling and enhanced PTH signaling can explain the correlation between osteoporosis and atherosclerosis in RA patients." (PMID 34641970, 2021).
osteoporosis (continued). "Parathyroid hormone (PTH) provides anabolic therapy for osteoporosis clinically as it has been documented to increase bone mineral density and to reduce the rate of fractures in patients with osteoporosis and also improve fragility fracture-healing." (PMID 34776985, 2021). "Currently molecules such as PTH analogue (iPTH) are used as a treatment for osteoporosis to trigger an increase in bone mass." (PMID 32183690, 2020). "The surge in parathyroid hormone (PTH) concentration induced by a high-phosphorus diet is considered to have positive correlations with diseases or syndromes of osteoporosis and low bone density triggered by ageing." (PMID 33142962, 2020). "Intermittent PTH administration has been used for clinical bone stimulation in osteoporosis patients for decades." (PMID 32431614, 2020). "In recent years, Wnt/β-catenin activation and PTH (parathyroid hormone) have been studied for the treatment of osteoporosis and the promotion of fracture healing." (PMID 32075627, 2020). "Patients with osteoporosis and osteopenia had significantly higher serum levels of PTH (792.9 and 469.7) (p<0.05)." (PMID 33180791, 2020). "Given the essential regulatory roles of T cells for the PTH-induced bone loss, particular attention will be paid toward the combinations of intermittent PTH (iPTH) and T cell therapy for PTH-induced osteoporosis." (PMID 32849268, 2020). "Limited data are available regarding the use of recombinant human PTH (rPTH) in osteoporosis treatment among renal transplant recipients." (PMID 32575603, 2020). "Calcilytics were developed to treat osteoporosis by a bone-anabolic effect and mimics an intermittent PTH treatment." (PMID 32117726, 2020). "The biochemical parameters derived from secondary osteoporosis, such as serum vitamin D and parathyroid hormone (PTH), among others, should also be assessed." (PMID 32722015, 2020). "In clinical settings, patients who fail conventional anti-osteoporosis therapy with bisphosphonates or have recurrent fractures are usually switched to PTH treatment." (PMID 33584284, 2020). "In another study, Yang Y. and colleagues fabricated a novel class of bone-targeting anabolic compound based on PTH-PEG-BP (parathyroid hormone- polyethylene glycol-bisphosphonate) for the treatment of osteoporosis and related bone disorders." (PMID 33271770, 2020). "PTH and FGF-23 promote bone resorption and reduce bone mineralisation, respectively, and are both implicated in osteoporosis." (PMID 32185580, 2020). "The existing approved drugs for osteoporosis include bisphosphonates, ecombinant human parathyroid hormone (PTH), hormone replacement therapy (HRT), selective estrogen receptor modulators (SERMS), and denosumab." (PMID 32616823, 2020). "In patients with PHPT, long-term increases in PTH levels can lead to bone lesions such as osteoporosis, fragility fractures, and bone pain, as well as kidney lesions such as kidney stones, kidney calcification, and reduced renal function." (PMID 32973674, 2020). "On the other hand, a bone anabolic agent, teriparatide (a parathyroid hormone analog), has recently been used for osteoporosis treatment." (PMID 32493422, 2020). "Anti-resorptive agents such as bisphosphonates, selective estrogen receptor modulators (SERMs), and anabolic drugs that stimulate bone formation, including PTH analogs and sclerostin inhibitors, are current treatments for osteoporosis." (PMID 32582688, 2020). "Using recently published literature, we aimed to review the effect of using PTH and antiresorptive drugs as a combination therapy for osteoporosis treatment and evaluate the best treatment option." (PMID 33584284, 2020). "Recombinant human parathyroid hormone (PTH or teriparatide) has anabolic effects on bone formation by acting on osteoblasts, and has been approved to treat osteoporosis." (PMID 33553146, 2020).
osteoporosis (continued). "Recent treatment and prevention strategies of osteoporosis involve the use of antiresorptive agents (bisphosphonates and selective estrogen receptor modulators) and anabolic agents (parathyroid hormone)." (PMID 33293993, 2020). "Although there are several drugs used to treat osteoporosis in clinical practice, such as parathyroid hormone or bisphosphonates, they all have some serious side effects." (PMID 33415157, 2020). "The rationale for developing such compounds stemmed from the requirement of alternative small molecule calcilytics for treating osteoporosis; the standard of care at that time being anabolic therapies using PTH analogs (teriparatide) and PTH-related peptides." (PMID 32117726, 2020). "Conventional therapy for osteoporosis includes the administration of calcium, bisphosphonate, or PTH." (PMID 33109775, 2020). "Although many previous studies showed that teriparatide was effective for osteoporosis treatment, the combination of parathyroid hormone (PTH) and alendronate was inferior to PTH alone in preventing loss of lumbar BMD." (PMID 31948455, 2020). "In addition, high creatinine, low 25(OH)D, high β-CTX, and high PTH may increase osteoporosis risk." (PMID 33315972, 2020). "Most of the patients in the denosumab treatment groups did receive other osteoporosis medications previously, including bisphosphonates, estrogen, strontium ranelate, or parathyroid hormone." (PMID 32499755, 2020). "This study also adds further evidence that high serum PTH levels is associated with low BMD and makes the patients at increased risk of osteoporosis and bone fractures." (PMID 33180791, 2020). "Combination therapy initiated in naïve patients with osteoporosis or PTH therapy initiated after pre-alendronate monotherapy also significantly influences the outcomes." (PMID 33584284, 2020). "Among these drugs, human parathyroid hormone hPTH is of great interest as a therapeutic agent for osteoporosis." (PMID 32850709, 2020). "For the Hip BMD, Post hoc analysis showed that PTH is significantly higher among osteoporosis group compared to osteopenia group (P = 0.006) and compared to normal group (P = 0.034)." (PMID 33180791, 2020). "In support of this, PTH has been shown to have a therapeutic effect in osteoporosis in affected human patients." (PMID 32582784, 2020). "PTHR1 mediates the biological activity of PTH in treating osteoporosis, whereas the function of PTHR2 is more obscure." (PMID 32350260, 2020). "On the other hand, DHEA for 12 weeks corrected hypogonadism-induced osteoporosis in male rats probably via inhibiting osteoclastogenesis, stimulating the activity of osteoblasts and stimulating the secretion of PTH and testosterone." (PMID 33238425, 2020). "Teriparatide (TPTD) is a bioactive recombinant form of parathyroid hormone that is approved for osteoporosis treatment." (PMID 32799756, 2020). "Currently, two parathormone (PTH) analogues, PTH 1–34 (or teriparatide) and PTH 1–84, are available for clinical treatment of osteoporosis." (PMID 32102398, 2020). "Currently, estrogen treatment or hormone replacement therapy, antiresorptive agents like bisphosphonates and anabolic agents like Parathyroid Hormone (PTH) have emerged as potential therapeutics for osteoporosis treatment." (PMID 31555218, 2019). "Although PTH and bisphosphonates are used for the treatment of osteoporosis, their actions are distinct." (PMID 31844831, 2019). "PTH is the first bone anabolic drug approved for the treatment of osteoporosis, preventing the delay of fracture healing due to aging." (PMID 31718681, 2019). "Despite their side effects, anabolic agents, such as recombinant human parathyroid hormone and its amino terminal fragment teriparatide, have been approved for the treatment of osteoporosis." (PMID 30670092, 2019). "The role of parathyroid hormone (PTH) in treating osteoporosis is generally accepted, but the effect of PTH on fracture healing is controversial." (PMID 31038646, 2019).
osteoporosis (continued). "Prevention of this fracture is possible by treating osteoporosis with diet and drugs, including vitamin D, calcium, bisphosphonate medications, and recombinant human parathyroid hormone (PTH)." (PMID 33467341, 2019). "Parathyroid hormone (PTH) is currently the only FDA-approved anabolic medicine for osteoporosis in the USA." (PMID 31661767, 2019). "Parathyroid hormone (PTH) tightly regulates the homeostasis and functioning of all types of bone cells, and has been approved for clinical treatment of osteoporosis." (PMID 31666998, 2019). "The results of the study strongly indicated that PTH (1‐84) treatment promoted healing of pelvic fractures in elderly patients with severe osteoporosis." (PMID 31844831, 2019). "One way to treat osteoporosis is by injection of the bone anabolic peptide parathyroid hormone (PTH)." (PMID 31572390, 2019). "The FDA has also approved the anabolic agent, human parathyroid hormone (PTH) peptide, to treat osteoporosis." (PMID 31024360, 2019). "Parathyroid hormone-based drugs, such as teriparatide, are commonly used to treat osteoporosis by promoting osteogenesis." (PMID 31098335, 2019). "Conversely, intermittent PTH (iPTH) creates a potent anabolic effect on bone, which forms the basis of an effective osteoporosis therapy." (PMID 31713180, 2019). "Teriparatide is a human recombinant parathyroid hormone, anabolic on bone and it is recommended for the treatment of post-menopausal osteoporosis." (PMID 30823566, 2019). "Analogs of parathyroid hormone (teriparatide and abaloparatide), given by daily subcutaneous injections, are the currently available anabolic therapies for osteoporosis." (PMID 30622831, 2019). "In summary, intermittent administration of PTH increases bone mass and has been approved as a therapeutic agent for the treatment of osteoporosis." (PMID 31844831, 2019). "Although African-Americans typically resent lesser intake of calcium in the diet than Caucasians, they have a higher bone density, with lower rates of osteoporosis, and skeletal resistance to the effects of the parathyroid hormone." (PMID 30278805, 2018). "Parathyroid hormone (PTH) is one of the approved anabolic candidates used for the treatment of osteoporosis in developed countries." (PMID 30287779, 2018). "PTH is able to exert anabolic effects upon intermittent administration; clinically used as osteo-anabolic therapy for the treatment of osteoporosis." (PMID 29547116, 2018). "Zosano Pharma Corporation has developed a transdermal MN product based on solid titanium MNs coated with recombinant human parathyroid hormone 1-34, teriparatide (PTH, 4.1 kDa), for the management of osteoporosis." (PMID 29497609, 2018). "ZP-PTH®, a PTH-coated titanium microneedle patch system, with needle length 190 μm, was developed for the treatment of osteoporosis." (PMID 30400376, 2018). "The safety and efficacy of PTH in MM are therefore still to be established, but warrant further enquiry given promising results obtained in patients with osteoporosis." (PMID 29098361, 2018). "Parathyroid hormone (PTH) has been shown to have anabolic affects in bone remodelling in osteoporosis." (PMID 29098361, 2018). "Continued research into the regulatory mechanisms of PKA and ERK for PRGs will help us better understand the molecular mechanisms underlying the dual effects of PTH, thereby optimizing the current therapeutic use of PTH for osteoporosis." (PMID 30576321, 2018). "Several factors, such as parathyroid hormone (PTH) and bone morphogenetic proteins (BMPs), have been used for osteoporosis treatment and bone regeneration, respectively." (PMID 29348519, 2018). "PTH concentrations were lower in the menopausal groups with low BMD/osteoporosis compared to normal BMD groups." (PMID 29789485, 2018).
osteoporosis (continued). "Majority of the existing treatments for osteoporosis such as recombinant parathyroid hormone (PTH), bisphosphonates, and selective estrogen receptor modulators (SERMS) have multiple side effects and new therapeutics are desperately needed." (PMID 29987256, 2018). "Efficient transdermal delivery of PTH and treatment of osteoporosis were successfully achieved by application of PTH-loaded MNs without the development of any skin irritation." (PMID 30400376, 2018). "The main findings of this study are as follows: (i) LMHF loading and PTH have additive effects on peri-implant bone healing and implant osseointegration in osteoporosis model." (PMID 29531334, 2018). "PaVOS is a randomized controlled trial (RCT) which aims to address the use of whole-body vibration exercise (WBV) in combination with parathyroid hormone 1-34 fragment teriparatide (PTH 1-34) treatment in patients with osteoporosis." (PMID 29548300, 2018). "In the present study, bone formation was observed by application of PTH-loaded MNs twice a week, and the therapeutic effects of PTH-loaded MNs on osteoporosis were proportional to the pharmacokinetics of PTH after application of PTH-loaded MNs." (PMID 30400376, 2018). "Ultimately, a thorough understanding of how intermittent PTH therapy affects bone will be necessary to design new and improved future osteoporosis treatments." (PMID 30283888, 2018). "In fact, teriparatide (TPTD), the N-terminal 34 amino acids fragment of PTH, is currently the only bone anabolic agent used for the treatment of osteoporosis, by daily or weekly subcutaneous administration." (PMID 29725706, 2018). "In the present study, we developed an efficient transdermal delivery system of PTH by using dissolving microneedle arrays (MNs) composed of hyaluronic acid (HA) for the treatment of osteoporosis." (PMID 30400376, 2018). "The parathyroid hormone 1-34 fragment teriparatide (PTH 1-34) is the most commonly used anabolic agent for the treatment of osteoporosis." (PMID 29548300, 2018). "Toru Ogawa of Tohoku University Graduate School of Dentistry in Sendai, Japan, and colleagues gave anti-osteoporosis medications, either parathyroid hormone or the bisphosphonate drug alendronate, to female rat models of osteoporosis." (PMID 29531334, 2018). "Targeted delivery and transcription of genes encoding critical regulators in bone remodelling including BMPs, PTH or OPG has proven efficient to treat experimental osteoporosis." (PMID 30587780, 2018). "The protective effect of obesity on osteoporosis was complicated by the effect of obesity on vitamin D and PTH." (PMID 28124221, 2017). "In our study, PTH was significantly higher in diabetes group than control group, and it was significantly higher in diabetic osteoporosis group than osteopenia group and normal BMD group." (PMID 29190676, 2017). "Intermittent Parathyroid Hormone (I-PTH) is the only FDA approved anabolic drug therapy available for the treatment of osteoporosis in males and postmenopausal females." (PMID 28607469, 2017). "In osteoporosis, normal levels of serum calcium, phosphate, alkaline phosphatase, and PTH are present; by contrast, abnormalities in at least one of these measurements are common in osteomalacia." (PMID 28851305, 2017). "BMI was positively correlated with BMD and PTH but negatively correlated with vitamin D. Logistic regression showed that the odds ratio (OR) for having osteoporosis decreased with increasing BMI (overweight OR = 0.11, p = 0.053; obese OR = 0.05, p = 0.007)." (PMID 28124221, 2017). "Several studies have demonstrated that intermittent PTH treatment induces remedial action against osteoporosis due to anabolic effects on bone tissue." (PMID 28694469, 2017). "On the other hand, our previous study assessed the effects of intermittent PTH administration initiated before implant placement in rabbit models with osteoporosis." (PMID 29069147, 2017).